TLR4 (toll like receptor 4)
Diseases named in the same sentence as TLR4 in open-access papers (continued):
Sharing a sentence is not in itself a finding about the gene and the disease.
retinopathy (10 papers, 2015 to 2026). "TLR4 polymorphisms were associated with a higher prevalence of retinopathy, further supporting the role of this gene in DR." (PMID 37371657, 2023). "We also found that TLR4 deficiency could protect mice from angiogenesis in oxygen-induced retinopathy model." (PMID 26468333, 2015). "Toll-like receptor 4 polymorphisms was associated with a higher prevalence of retinopathy." (PMID 26468333, 2015). "Low TLR4 levels in retinal endothelial cells have demonstrated protection against retinopathies." (PMID 39195259, 2024). "In an oxygen-induced retinopathy model, the absence of TLR4 was seen to be associated with low glial activation and low expression of HMGB-1, the endogenous ligand for TLR4." (PMID 37371657, 2023).
psychiatric disorder (9 papers, 2018 to 2025). A disorder characterized by behavioral and/or psychological abnormalities, often accompanied by physical symptoms. "Interestingly, we found that 10Hz flicker mitigated stress-induced changes in transcription of microglial receptors P2ry12 and stress associated receptors such as Nr3c1 and Tlr4, as well as microglial Igfbp2, a key gene implicated in affective and psychiatric disorders." (PMID 40791511, 2025). "Considerable evidence suggests that type I IFN is associated with psychiatric disorders, and that the production of type I IFNs as a result of TLR4 induced IRF3 activation and TLR7 induced IRF7 activation may be closely associated with IFN-mediated psychiatric disorders." (PMID 36325336, 2022). "TLR4 deficiency could induce microglial polarization toward the M2 phenotype and downregulating pro‐inflammatory cytokines, which may contribute to the prevention of psychiatric disorders." (PMID 31945269, 2020). "Nevertheless, we detected four inherited rare variants of unknown significance in four respective genes implicated in psychiatric disorders in the patient, including p.Arg1627Trp of LAMA2, p.Arg691Gly of TLR4, p.Pro1338Ser of CSMD1, and Arg182X of AGTR2." (PMID 37511534, 2023). "Other evidence supporting the role of TLR4 on psychiatric diseases come from animal models." (PMID 34267256, 2021). "In human postmortem studies of psychiatric disorders, TLR4 has been found to have been altered." (PMID 31647818, 2019).
gastrointestinal disease (8 papers, 2013 to 2026). A disease that occurs in the gastrointestinal system, excluding the hepatobiliary system. "In the treatment of gastrointestinal diseases, an increasing number of studies have focused on blocking the TLR4/NF-κB pathway." (PMID 41532082, 2025). "A growing number of studies have focused on blocking the TLR4/NF-κB pathway for the treatment of gastrointestinal diseases, but whether TLR4 binds to RV protein is unclear." (PMID 38555283, 2024). "In conclusion, DCPH alleviates gastric mucosal injury via regulating autophagy and targeting TLR4/NF-κB/NLRP3, thereby offering insights for the treatment of gastrointestinal diseases." (PMID 41982492, 2026). "A therapeutic strategy targeting TLRs to improve host immunity has been utilized to treat gastrointestinal disease by applying Lactobacillus species; for example, Lactobacillus crispatus can modulate epithelial cell defense against Candida albicans through the TLR2 and TLR4 pathways." (PMID 34322122, 2021).
hematologic malignancies (6 papers, 2017 to 2025). "This study provides a compelling case for targeting TLR4 signaling as a potential therapeutic strategy in hematological malignancies associated with del(5q) alterations." (PMID 40922674, 2025). "STAT3, IL5, and TLR4 normalized counts showed similar patterns to NGAL normalized counts in hematological malignancy and control groups." (PMID 34400898, 2021). "This study emphasizes the critical role of TLR4 signaling in maintaining the inflammatory microenvironment that promotes leukemic progression, providing a foundation for developing targeted therapies to modulate these pathways in hematologic malignancies." (PMID 40922674, 2025). "This study demonstrates that the integration of a truncated TLR4 signaling costimulatory domain could provide immunotherapeutic potential against both hematologic malignancies and solid tumors." (PMID 38840781, 2024). "The activation of the immune system is usually caused by direct contact between intestinal immune cells and microbial metabolites, which activates TLR4/MyD88/NF-kB signaling in B cells and the immune response, and promotes the progression of hematological malignancies." (PMID 37190210, 2023). "The rs5743551 (−7202G>A) variation in the TLR1 gene, the rs7656411 (22215G>T) variation in the TLR2 gene and the rs11536889 (+3725G>C) variation in the TLR4 gene were genotyped in 365 recipients with hematologic malignancies and their unrelated donors in the discovery cohort." (PMID 28484092, 2017). "This is consistent with prior studies showing CCRL2’s interaction with TLR4 in macrophages, enhancing its stability and supporting NF-κB activation, and its involvement in IFN-γ/STAT1 signaling in hematologic malignancies, even in the absence of exogenous cytokine." (PMID 40867595, 2025).
brain diseases (5 papers, 2012 to 2022). "Toll-like receptor 4 (TLR4) plays a role in inflammatory damage caused by brain disorders." (PMID 22394415, 2012). "Several other innate immune PRRs, such as TLR2, TLR4 and TLR9, have been implicated in the pathogenesis of bacterial, and specifically pneumococcal, brain disease, but in most cases in isolated cell culture conditions." (PMID 36028511, 2022). "However, there are many reports suggesting that microglia are important for TLR4-mediated immune responses, which may be involved in brain diseases such as AD18 and PD19." (PMID 26440368, 2015).
central nervous system diseases (5 papers, 2019 to 2023). "The TLR4/NF-κB signaling pathway is closely related to neuroinflammation in central nervous system diseases." (PMID 37351155, 2023). "The activation of the TLR4/MyD88 signaling pathway has been widely observed in central nervous system diseases, including AD." (PMID 34650664, 2021). "TLR4 has been identified as the major isoform of TLRs that trigger sterile inflammation in many central nervous system diseases." (PMID 34162400, 2021).
heart (5 papers, 2012 to 2020). "To date, the role played by TLR4 in the ischemic heart has remained inconclusive." (PMID 31817787, 2019). "TLR4 and TLR2 were identified as dynamic in mediating the inflammatory response in the ischemic heart." (PMID 31109132, 2019).
myopathy (4 papers, 2020 to 2026). A disease of the muscle in which the muscle fibers do not function properly. "In addition, the HMGB1-TLR4 pathways play an essential role in causing muscle fatigue in patients with myopathy because TLR4 is activated in mouse and human skeletal muscle fibers after HMGB1 stimulation." (PMID 36497194, 2022). "The expression of TLR4 in all monocyte subsets and the percentage of intermediate monocytes are related to the diagnosis of inflammatory myopathies with a high area under the curve, specificity and positive likelihood ratio (LR (+))." (PMID 32164729, 2020). "We found that the expression of TLR4 in all monocyte subsets and the percentage of intermediate monocytes predict the diagnosis of inflammatory myopathies with a high area under the curve and specificity." (PMID 32164729, 2020). "By activating the MyD88 signaling pathway and its downstream NF-κB pathway, TLR4 ultimately upregulates the strong pro-inflammatory factor IFN-γ and forms a pro-inflammatory myopathy environment." (PMID 36742332, 2023). "Previous studies have shown an increased gene expression of the TLR4 and IFN-γ signaling pathway in patients with inflammatory myopathies." (PMID 32164729, 2020). "Inhibition of TLR4 and HMGB1 signaling significantly reduced the expression of TNF-α and IL-6 cytokines in a myopathy mouse model, suggesting that the HMGB1/TLR4 axis may involve in skeletal muscle atrophy." (PMID 36497194, 2022).
bone disorder (3 papers, 2013 to 2025). "Differentiated osteoblasts also express functional TLR4, which seems to play an important role in the pathogenesis of LPS-induced bone disorders." (PMID 23638389, 2013).
neurodevelopmental disorder (3 papers, 2021 to 2025). A behavioral and cognitive disorder with onset during the developmental period that involves impaired or aberrant development of intellectual, motor, or social functions. "The associated SNPs map at the highly conserved ASTN2/BRINP1 locus at chr9q33.1–33.2, which contains five genes (ASTN2, BRINP1, TRIM32, TLR4 and C5) that have been previously associated with neurodevelopmental disorders (reviewed in29)." (PMID 34267256, 2021). "It should be added that LPS-induced maternal immune activation may have increased the vulnerability to such immune hits by inducing neurodevelopmental disorders with sensitized immune-inflammatory pathways (including in TLR4 and inflammasome) and lowered neuroprotection." (PMID 34831151, 2021).
endocrine diseases (2 papers, 2011 to 2024). "Aberrant regulation of the TLR4 signaling cascade is found to be correlated to many conditions, i.e., infectious diseases, metabolic disorders, immune diseases, endocrine diseases, acute organ injury, and drug addiction." (PMID 38504994, 2024).
vasculopathy (1 paper, 2020). "Patients with IIM have a differential pool of monocyte subsets with an enhanced expression of TLR2 and TLR4, which correlates with disease activity and distinctive clinical features including dysphagia, ILD, vasculopathy, and pro-inflammatory cytokines." (PMID 32164729, 2020).
TLR4 also shares sentences with these, for which no sentence is quoted: acute myocardial infarction (23 papers); multiple myeloma (13); primary open-angle glaucoma (10); renal failure (8); colon (7); nasopharyngeal carcinoma (7); alcoholic hepatitis (6); hypertrophy (6); vascular dementia (6); Candidemia (5); diarrhoea (5); idiopathic pulmonary fibrosis (5); portal hypertension (5); respiratory failure (5); Barrett esophagus (4); behavioral disorders (4); chronic lymphocytic leukemia (4); acute cystitis (3); autism spectrum disorder (3); basal cell carcinoma (3); chronic hepatitis C (3); graft versus host disease (3); leukopenia (3); obstructive jaundice (3); Parkinson (3); sleep disorder (3); viral diseases (3); Acidosis (2); aggressive periodontitis (2); amoebiasis (2).
A further 216 diseases each share a sentence with TLR4 in 2 papers or fewer.